SLC7A11 (solute carrier family 7 member 11)
Diseases named in the same sentence as SLC7A11 in open-access papers (continued):
Sharing a sentence is not in itself a finding about the gene and the disease.
alopecia (1 paper, 2023). Hair loss usually from the scalp. "In this study, SEL can significantly increase the expression of SLC7A11 and GCLM, thereby promoting the synthesis of GSH and inhibiting ferroptosis, leading to a positive effect on the treatment of alopecia." (PMID 37507872, 2023).
apical periodontitis (1 paper, 2025). "During the early phase of apical periodontitis, there is a response increase in the expression of GPX4 and SLC7A11 to protect the AP model from being damaged by ferroptosis." (PMID 39744165, 2025).
astrocytoma (1 paper, 2024). "Our study explored the effects of sevoflurane treatment on the offspring of pregnant mice and on the human astrocytoma cell line U251, focusing on the regulatory role of SLC7A11 in astrocyte ferroptosis and its interaction with sevoflurane." (PMID 39724413, 2024). "Additionally, pregnant mice were subjected to in vivo experiments, and in vitro studies using U251 astrocytoma cells were conducted to evaluate sevoflurane's neurotoxic effects on offspring, focusing on ferroptosis markers and SLC7A11 expression." (PMID 39724413, 2024).
Ataxia (1 paper, 2024). Ataxia refers to impaired coordination of voluntary muscle movement. "Furthermore, in a mouse model of ataxia (Kcna1‐KO), exhibiting enlarged hippocampus and aberrant adult neurogenesis, the levels of Slc7a11 mRNA are increased." (PMID 38757355, 2024).
Atrophy (1 paper, 2024). Any weakening or degeneration, especially through lack of use. "Shenshuai Yingyang Jiaonang has been shown to improve muscle atrophy associated with CKD-associated muscle atrophy in rats by inhibiting ferroptosis through the HIF-1α/SLC7A11 pathway." (PMID 39596528, 2024).
autism (1 paper, 2021). Persistent deficits in social interaction and communication and interaction as well as a markedly restricted repertoire of activity and interest as well as repetitive patterns of behavior. "Previously, a genome-wide linkage analysis of families with autism identified a susceptibility locus located on chromosome 4 in a region containing SLC7A11, the gene encoding xCT." (PMID 32366950, 2021). "Previous findings propose a possible genetic association between variation in SLC7A11 and susceptibility to autism." (PMID 32366950, 2021).
autism spectrum disorder (1 paper, 2021). A spectrum of developmental disorders that includes autism, and Asperger syndrome. "In addition, a rare missense variation in SLC7A11 has been recently identified in a small family with affected autism spectrum disorder siblings by whole-exome sequencing." (PMID 32366950, 2021).
choriocarcinoma (1 paper, 2023). An aggressive malignant tumor arising from trophoblastic cells. "In choriocarcinoma, vorinostat causes a decrease in the level of SLC7A11 protein through a reduction in the expression of SLC3A2, which may lead to deregulated xCT function." (PMID 36106577, 2023).
chronic kidney disease (1 paper, 2024). Impairment of the renal function secondary to chronic kidney damage persisting for three or more months. "The SLC7A11/GSH/GPX4 axis is a vital pathway that regulates ferroptosis through cystine metabolism and is closely linked to chronic kidney disease." (PMID 39472936, 2024).
chronic liver failure (1 paper, 2025). Liver failure that develops slowly and gradually for some time, possibly for years, often as the result of cirrhosis, or malnutrition. "Niujiao Dihuang Jiedu decoction has a significant therapeutic effect on acute-on-chronic liver failure, where it inhibited acute-on-chronic liver failure-related ferroptosis by promoting SLC7A11 m5C methylation, which is generated by binding to NSUN5." (PMID 41462962, 2025).
chronic myeloid leukemia (1 paper, 2025). "Similarly, Hyperoside induces ferroptosis in chronic myeloid leukemia cells by targeting the Nrf2/SLC7A11/GPX4 axis, with molecular docking, DARTS, and CETSA experiments demonstrating its high affinity for Nrf2." (PMID 40917752, 2025).
cobalamin deficiency (1 paper, 2021). "Genes related to stress response (ceremide kinase like) and nutrient metabolism (phosphoenolpyruvate carboxy-kinase 1, methylmalonic aciduria [cobalamin deficiency] cblB type, glycine receptor alpha 2, solute carrier family 7 member 11, etc.)were also identified to be differentially expressed." (PMID 33152221, 2021).
colorectal tumors (1 paper, 2025). "Multiple cancer studies show that METTL3-installed m6A marks on SLC7A11 can be read by IGF2BP proteins to stabilize the cystine transporter transcript, elevate glutathione synthesis, and suppress ferroptosis, and FTO likewise protects colorectal tumors by sustaining SLC7A11/GPX4 expression." (PMID 41280938, 2025).
disseminated candidiasis (1 paper, 2024). Systemic candidiasis occurs when Candida yeast enters the bloodstream and may spread (becoming disseminated candidiasis) to other organs, including the central nervous system, kidneys, liver, bones, muscles, joints, spleen, or eyes. "In conclusion, our work demonstrates that CARD9 ablation exacerbates acute kidney injury in disseminated candidiasis by enhancing ferroptosis of MDSCs, which is attributed to the lower expression of SLC7A11." (PMID 38566195, 2024).
dysplasia (1 paper, 2024). A usually neoplastic transformation of the cell, associated with altered architectural tissue patterns. "Immunoreactivity of c-Myc and SLC7A11 significantly intensified from normal cervical epithelium to dysplasia and CSCC stages (200 × magnification)." (PMID 39420439, 2024).
E. coli infection (1 paper, 2025). "E. coli infection suppresses solute carrier family 7-member 11 (SLC7A11)/glutathione peroxidase 4 (GPX4) expression in bovine mammary epithelial cells (BMECs), disrupts iron homeostasis and precipitates ferroptosis." (PMID 41413615, 2025). "In accordance with the in vitro findings, PTGS2 expression in BEECs increased as the duration of E. coli infection increased, whereas GPX4 expression significantly increased at 1 h post-infection, and SLC7A11, GPX4, and FTH1 expression significantly decreased at 5 h post-infection." (PMID 41413615, 2025). "E. coli infection activates GSK-3β through dephosphorylation at Ser9, active GSK-3β binds and degrades NRF2 via the proteasome pathway, and NRF2 suppression disrupts antioxidant defenses (SLC7A11/GPX4 and GCLC/GSH) and iron homeostasis (FTH1), triggering ferroptosis in BEECs." (PMID 41413615, 2025).
embryonal carcinoma (1 paper, 2021). A non-seminomatous malignant germ cell tumor characterized by the presence of large germ cells with abundant cytoplasm resembling epithelial cells, geographic necrosis, high mitotic activity, and pseudoglandular and pseudopapillary structures formation. "Strikingly, the transient CCDC6 silencing in GC-1 and in NTERA-2 embryonal carcinoma cells, resulted associated with an increase of xCT/SLC7A11 at mRNA and protein level." (PMID 34841108, 2021).
ependymoma (1 paper, 2015). A WHO grade II, slow growing tumor of children and young adults, usually located intraventricularly. "We noticed that SLC7A11, one of the system xc− genes, was amplified in 5 patients, which is evidence for the role of glutamate in ependymoma." (PMID 26185765, 2015).
Era (1 paper, 2025). "Consistent with Era treatment, ETEC infection decreased the expression of GPX4 and increased the mRNA levels of ChaC glutathione-specific gamma-glutamylcyclotransferase 1 (CHAC1) and solute carrier family 7 member 11 (SLC7A11)." (PMID 40867813, 2025).
fibrosis (1 paper, 2025). the formation of excess fibrous connective tissue in an organ or tissue in a reparative or reactive process. "Future research should explore how SLC7A11 modulates immune cells and their interactions with other cell types within organs, thereby improving our understanding of the role of the immune system in fibrosis." (PMID 40249927, 2025).
folic acid deficiency (1 paper, 2025). "In HT-22 cells with SLC7A11 knockdown, the expression levels of ferroptosis inhibitory proteins SLC7A11, GPX4, and FTH1 were significantly reduced, particularly under conditions of folic acid deficiency." (PMID 40724917, 2025).
gallstones (1 paper, 2025). Solid crystalline precipitates in the biliary tract, usually formed in the gallbladder, resulting in the condition of cholelithiasis. "involving bile samples from 48 patients with CCA and 48 patients with gallstones, it was observed that the expression of Syncytin-1 and SLC7A11 in bile cfDNA gradually increased across groups with gallstones, stage I-II CCA, and stage III-IV CCA." (PMID 41487574, 2025).
gestational diabetes (1 paper, 2025). Carbohydrate intolerance first diagnosed during pregnancy. "Ferroptosis and gestational diabetes mellitus (GDM) converge at multiple molecular intersections, notably through the involvement of key regulatory genes including GPX4, SLC7A11, ACSL4, and LPCAT3." (PMID 41020807, 2025).
glaucoma (1 paper, 2023). Increased pressure in the eyeball due to obstruction of the outflow of aqueous humor. "Western blot analysis showed that the expression of Slc7a11 and GPX4 in the retinas of the glaucoma patients was downregulated compared with the healthy control subjects." (PMID 37371903, 2023). "The Slc7a11 immunofluorescence staining intensity was decreased in the retinas of patients with glaucoma compared with those of those nonglaucoma donors (normal subjects)." (PMID 37371903, 2023).
Hepatitis (1 paper, 2025). Inflammation of the liver. "Moreover, the absence of CAV1 exacerbated the susceptibility to ConA-induced hepatitis by decreasing SLC7A11 levels." (PMID 40180904, 2025).
hereditary hemochromatosis (1 paper, 2024). An inherited metabolic disorder characterized by iron accumulation in the tissues. "In a mouse model of hereditary hemochromatosis, iron overload-induced ferroptosis in the liver was associated with the increase in Slc7a11 expression." (PMID 39459368, 2024).
Hodgkins lymphoma (1 paper, 2022). A heterogeneous group of malignant lymphoid neoplasms of B-cell origin characterized histologically by the presence of Hodgkin and Reed-Sternberg (HRS) cells in the vast majority of cases. "Based on the bioinformatic analysis, SLC7A11 is also a regulator for ferroptosis in EBV positive hodgkin lymphoma (HL)." (PMID 36483594, 2022).
hypopharyngeal carcinoma (1 paper, 2026). Carcinoma, predominantly squamous cell, arising from the epithelial cells of the hypopharynx.
ischemia reperfusion injury (1 paper, 2025). Adverse functional, metabolic, or structural changes in ischemic tissues resulting from the restoration of blood flow to the tissue (reperfusion), including swelling; hemorrhage; necrosis; and damage from free radicals. "In ischemia-reperfusion injury (IRI), a well-established model for myocardial injury, ozone pre-treatment mitigates myocardial ferroptosis by activating the Nrf2/solute carrier family 7 member 11 (Slc7a11)/GPX4 axis." (PMID 40308274, 2025).
keratoconus (1 paper, 2023). A degenerative, structural disorder of the eye, characterized by a cone-shaped protrusion of the cornea. "We overlaid these 4 modules with FRGs and found that 8 FRGs (LCE2C, NOS2, AKR1C3, CAV1, MMD, LINC00618, SNCA, SLC7A11) were closely related to the disease state of keratoconus." (PMID 37626095, 2023).
left ventricular hypertrophy (1 paper, 2025). Enlargement of the LEFT VENTRICLE of the heart. "One study demonstrated that FTH maintains cardiac homeostasis and alleviates left ventricular hypertrophy in mice through involvement of SLC7A11 and Fer-1, a ferroptosis inhibitor." (PMID 40158182, 2025).
male reproductive disease (1 paper, 2025). "Regulation SLC7A11 levels exhibits potential in treating ferroptosis-induced male reproductive disease." (PMID 38797476, 2025). "The discovery of SLC7A11 as a pivotal modular of ferroptosis provides opportunities to improve ferroptosis-based male reproductive disease therapy." (PMID 38797476, 2025).
metastatic tumors (1 paper, 2024). "The expressions of both cystine transporters (SLC7A11, SLC3A2) and cysteine transporters (SLC1A4, SLC1A5) were significantly upregulated in CRC compared with paired non-tumor tissues, but were similar in primary tumors and metastatic tumors." (PMID 39079386, 2024).
Miscarriage (1 paper, 2026). A pregnancy that ends at a stage in which the fetus is incapable of surviving on its own, defined as the spontaneous loss of a fetus before the 22th week of pregnancy. "In this study, based on two UM case-control groups, four ZnCl2-exposed mouse models, and a ZnCl2-exposed trophoblast Swan 71 cell model, we obtain a consistent conclusion that excessive Zn exposure causes disulfidptosis and thus induces miscarriage by up-regulating the GATA1/METTL1/SLC7A11 axis." (PMID 42095470, 2026). "Knockdown of murine Slc7a11, Gata1, or Mettl1, or supplement with NADPH suppresses mouse placental disulfidptosis and alleviates mouse miscarriage." (PMID 42095470, 2026).
oligodendroglioma (1 paper, 2023). A well-differentiated (WHO grade II), diffusely infiltrating neuroglial tumor, typically located in the cerebral hemispheres. "Consistent with this, CIC restoration in an oligodendroglioma line reduced the levels of extracellular glutamate, neuronal toxicity and xCT/SLC7A11 expression." (PMID 36647117, 2023).
osteomyelitis (1 paper, 2024). An acute or chronic inflammation of the bone and its structures due to infection with pyogenic bacteria. "In mice models of acute and subacute implant-associated osteomyelitis, we observed a slightly increased protein level of SLC7A11 at day 3 post-infection, peaking at days 7 and 14 post-infection." (PMID 38725861, 2024). "This study elucidates a close association between aberrantly activated SLC7A11 signaling and immunosuppressive state of macrophages in S. aureus-induced osteomyelitis." (PMID 38725861, 2024). "On the basis of our recent study on PD-L1 and the present study, we have further identified SLC7A11 as another important therapeutic target in macrophages for prevention of persistent infection in a setting of subacute S. aureus osteomyelitis." (PMID 38725861, 2024). "Before comparing the severity of S. aureus osteomyelitis in Lyz2Cre-Slc7a11f/f mice with that in Slc7a11f/f mice, we evaluated the protein levels of SLC7A11 in BMDMs from these mice." (PMID 38725861, 2024). "We subsequently investigated the role of SLC7A11 in the pathological development of S. aureus osteomyelitis in vivo." (PMID 38725861, 2024). "It is worth noting that a combination blockade of both SLC7A11 and PD-L1 signaling strongly promoted clearance of S. aureus and improved resolution of osteomyelitis in mice." (PMID 38725861, 2024). "Together, these findings identify SLC7A11 as a novel molecular target in a combination immunotherapy for S. aureus-induced osteomyelitis." (PMID 38725861, 2024). "We demonstrated that pharmacological inhibition or genetic knockout of SLC7A11 can promote bactericidal function of macrophages, reduce bacterial burden in the bone and improve bone structure of mice with S. aureus osteomyelitis." (PMID 38725861, 2024). "Although the immune activation mediated by SLC7A11 blockade has shown a promising therapeutic potential for S. aureus-induced osteomyelitis, there are still several aspects that warrant further investigation." (PMID 38725861, 2024). "Our findings suggest that targeting both SLC7A11 and PD-L1 is a promising therapeutic approach to reprogram the bactericidal function of macrophages and promote bacterial clearance in S. aureus osteomyelitis." (PMID 38725861, 2024). "Flow cytometry analysis revealed a significant increase in SLC7A11 expression levels in CD11b+F4/80+ macrophages as early as day 3 post-infection, which further increased as S. aureus osteomyelitis progressed." (PMID 38725861, 2024). "Importantly, pharmacological inhibition or genetic knockout of SLC7A11 promoted the bactericidal function of macrophages, reduced bacterial burden in the bone and improved bone structure in mice with S. aureus osteomyelitis." (PMID 38725861, 2024). "Consistent with the effect of the pharmacological inhibitor erastin on ROS levels in S. aureus-infected osteomyelitis mice, specific knockout of Slc7a11 in macrophages significantly enhanced ROS production and lipid peroxidation metabolism in mice with S. aureus osteomyelitis." (PMID 38725861, 2024). "However, the role and mechanism of SLC7A11 in S. aureus-induced osteomyelitis remain poorly understood." (PMID 38725861, 2024). "Taken together, these results suggest that aberrant expression of SLC7A11 may have detrimental effects on bacterial clearance by suppressing ROS levels in macrophages in S. aureus-induced osteomyelitis mice." (PMID 38725861, 2024). "Given the intracellular persistence of S. aureus within macrophages during osteomyelitis pathogenesis, SLC7A11 overexpression may render cells more resistant to oxidative stress induced by intracellular bacteria, thus protecting cells from death and facilitating S. aureus persistence." (PMID 38725861, 2024).
parasite (1 paper, 2020). "Specifically, blocking GPX4 or SLC7a11 dramatically reduces Plasmodium liver stage parasite infection." (PMID 31065106, 2020).
prostatitis (1 paper, 2022). An infectious or non-infectious inflammatory process affecting the prostate gland. "Moreover, elevated iron concentration and differential expression of ferroptosis indicators, including GPX4, SLC7A11/Xc−, ACSL4, LPCAT3, and PTGS2, implied that ferroptosis engaged in the development of prostatitis in the context of iron overload and oxidative damage." (PMID 35755168, 2022).
relapsing-remitting multiple sclerosis (1 paper, 2022). The most common clinical variant of multiple sclerosis, characterized by recurrent acute exacerbations of neurologic dysfunction followed by partial or complete recovery. "Reduced expression of SLC7A11 impairs proliferative capacity of Tregs from the patients with relapsing-remitting multiple sclerosis (RRMS)." (PMID 35720275, 2022).
Renal cyst (1 paper, 2024). A fluid filled sac in the kidney. "We found that SLC7A11 was expressed in very low levels in MCT but was upregulated (4.9×) in renal cysts." (PMID 39000280, 2024).
renal tumors (1 paper, 2024). "SLC7A11, HMOX1, and MT1G were the 3 FRGs associated with the prognosis of adrenocortical carcinoma (ACC), KICH, KIRC and KIRP, while the SLC7A11 is a prognostic risk factor for above 4 different renal tumors, and high expression of MT1G increases the prognostic risk of ACC, ccRCC and chRCC." (PMID 39399506, 2024).
retinoblastoma (1 paper, 2024). A malignant tumor that originates in the nuclear layer of the retina. "We also discovered that the activation of SLC7A11 was fully regulated by GCN2 upon arginine deprivation, but individual knockdown of SLC7A11 rendered retinoblastoma cells resistant to arginine deprivation." (PMID 39462426, 2024). "Collectively, our findings suggest that the GCN2‒SLC7A11 axis regulates cell growth and survival upon arginine deprivation through coordinating autophagy, cell cycle arrest, and apoptosis in retinoblastoma cells." (PMID 39462426, 2024). "Knockdown of SLC7A11 rendered retinoblastoma cells partially resistant to arginine deprivation." (PMID 39462426, 2024).
schwannoma (1 paper, 2022). A benign, usually encapsulated slow growing tumor composed of Schwann cells.